RN7SL14P (RNA, 7SL, cytoplasmic 14, pseudogene)
Gene: Miscellaneous RNA gene on chromosome 20 (18,258,554 to 18,258,851, reverse strand). Ensembl gene ENSG00000266720.
Homologues: Orthologues: chimpanzee Metazoa_SRP (98% identical), macaque Metazoa_SRP (95% identical). Paralogues in human: RN7SL1 (87% identical), RN7SL2 (87% identical), RN7SL3 (86% identical), RN7SL296P (84% identical), RN7SL478P (83% identical), RN7SL126P (83% identical), RN7SL566P (83% identical), RN7SL679P (83% identical), RN7SL278P (82% identical), RN7SL556P (82% identical), RN7SL145P (82% identical), RN7SL220P (82% identical), and 703 more.